VWF (von Willebrand factor)
Diseases named in the same sentence as VWF in open-access papers (continued):
Sharing a sentence is not in itself a finding about the gene and the disease.
atherosclerosis (continued). "In addition, higher levels of vWF have been associated epidemiologically with atherosclerosis, in the coronary, cerebrovascular, and peripheral arterial beds." (PMID 29023508, 2017). "A few studies have shown an association between blood group alleles and vascular disease, including atherosclerosis, which is thought to be due to the higher level of von Willebrand factor in these individuals and the association of blood group locus variants with plasma lipid levels." (PMID 25592833, 2015). "Significant association of vWF activity and subclinical atherosclerosis in RA patients with low cardiovascular risk as well as its correlation with inflammation markers and disease activity implicates a pathophysiological link between RA and endothelial damage." (PMID 26247590, 2015). "Alternatively, protective effects of C1q-vWF could potentially also be related to an attenuation of downstream classical pathway complement activation, which has been associated with the progression of atherosclerosis." (PMID 38155969, 2023). "Furthermore, vWF deficiency protects against atherosclerosis in arterial branches." (PMID 35402552, 2022). "However, this is contrary to previous research, which shows that vWF or P-selectin deficiency can reduce atherosclerotic lesions, suggesting that VWF and P-selectin may also affect atherosclerosis by binding to other receptors instead of GPIb." (PMID 33371312, 2020). "The LNP-siRNA targeting Vwf strongly reduced plasma and endothelial VWF in mice with hypercholesterolemia and advanced atherosclerosis, indicating feasibility to target endothelial VWF under proatherothrombotic conditions." (PMID 40093962, 2025). "Studies have reported reduced ADAMTS13 activity or elevated VWF/ADAMTS13 ratios in young patients with atherosclerosis, including those with PAD." (PMID 41009700, 2025). "Recent studies have reported that blood vWF plays an important role in the development of thrombus formation and atherosclerosis." (PMID 40135640, 2025). "Relevance to atherosclerosis and restenosis: understanding the interplay between vWF, platelets, and collagen is crucial in the context of atherosclerosis and post-angioplasty restenosis, where platelet activation can lead to adverse thrombotic events." (PMID 40699681, 2025). "VWF is a glycoprotein function in hemostasis, and is secreted by the endothelial cells and megakaryocytes and involved in atherosclerosis." (PMID 37240845, 2023). "The net effect of complement activation in atherosclerosis appears to be regulated independently of C1q-vWF interaction." (PMID 38155969, 2023). "In population-based stuides, plasma levels of vWF are markedly higher in patients with atherosclerosis, and vWF are positively correlated with the plaque thickness and stenosis area." (PMID 37264012, 2023). "As evidence for a cross-talk between complement activation and hemostasis on CC surfaces has been limited to in vitro data, the aim of this study was to demonstrate the presence of C1q-vWF complexes in human atherosclerosis ex vivo." (PMID 38155969, 2023). "It has been reported that suppression of VWF in an animal model with atherosclerosis decreases the inflammation and the size of the plaque, as well as the adhesion of platelets." (PMID 37240845, 2023). "This study describing C1q and vWF deposition in atherosclerosis provides further insights into the steadily growing evidence of a cross-talk between complement and hemostasis." (PMID 38155969, 2023). "Here, we demonstrate the presence and co-localization of C1q and vWF in the intima of human carotid arteries, which is occurring predominantly in healthy tissue and is reduced in atherosclerosis." (PMID 38155969, 2023). "vWF activity was higher in RA patients with subclinical atherosclerosis (p<0.05) or atherosclerotic plaques (p<0.05)." (PMID 36249997, 2022).
atherosclerosis (continued). "Another ligand of STAB2, von Willebrand Factor (vWF), mediates vascular inflammation and enhances atherosclerosis by stimulating the adhesion of platelets onto the vessels." (PMID 35360009, 2022). "The release of VWF increases with endothelial cell damage, and elevated plasma VWF levels are usually observed in patients with hypertension and atherosclerosis." (PMID 36137144, 2022). "In our study, BAFF was positively correlated with DPB, LGI, and vWF—a known marker of ED and atherosclerosis." (PMID 35629302, 2022). "It was shown in a murine model that an increased VWF-mediated platelet adhesion to the endothelium characterizes the early stage of atherosclerosis." (PMID 36553147, 2022). "VWF-positive endothelial cells were observed in atherosclerosis lesions of GF-ApoE-/- rats from 13 to 52 weeks." (PMID 35522651, 2022). "The high expression of VWF relates to endothelial damage and is used for indicating many pathological situations, including atherosclerosis, cardiovascular diseases, and cancers." (PMID 33968738, 2021). "Further, VCAM-1, platelet glycoprotein (GP) Ibα, junctional adhesion molecule A (JAM-A), GP VI, lectin-type oxidized low-density lipoprotein receptor 1 (LOX-1), and von Willebrand factor (VWF) have been used for atherosclerosis imaging." (PMID 32998422, 2020). "Nevertheless, further investigation on the occurrence of CC-C1q-vWF complexes in human atherosclerosis is needed." (PMID 31824501, 2019). "Tissue factor (TF), PAI-1, and Von Willebrand factor (vWF) are pro-thrombotic mediators, which have been involved in endothelial activation and atherosclerosis pathogenesis." (PMID 31396153, 2019). "This is quite surprising since vWF genetic depletion is protective in an animal model of atherosclerosis." (PMID 31572732, 2019). "Factors promoting thrombosis such as von Willebrand factor (vWF) and P-selectin are essential for the development of atherosclerosis (AS) and arterial thrombosis." (PMID 31450612, 2019). "Past studies have explained that the platelet aggregation and adhesion is regulated by release of vWF, and subsequently, the high level of vWF has been attributed indirectly to atherosclerosis and thrombogenesis." (PMID 29785538, 2018). "In experimental models, VWF supports the activation of multiple inflammatory pathways, such as complement cascade and NETosis, promotes atherosclerosis favoring plaque progression and complication, and exacerbates ischemia/reperfusion injury." (PMID 28634421, 2017). "In the ECs of the atherosclerotic lesion, there is a high concentration of WPBs (in which the VWF in stored) and oxidized LDLs and high-shear stress, two factors involved in atherosclerosis, can induce WPB exocytosis." (PMID 28634421, 2017). "In the entire study population, vWF activity was higher in participants with subclinical atherosclerosis (130±68% vs. 97±38%, p<0.05) or atherosclerotic plaques (123±57% vs. 99±45%, p<0.05) than in those without." (PMID 26247590, 2015). "Predictive value of vWF activity for subclinical atherosclerosis was confirmed by logistic regression." (PMID 26247590, 2015). "The vWF is considered a reliable marker of endothelial dysfunction/damage, which is an initial step in atherosclerosis." (PMID 26247590, 2015). "vWF:Ag is a marker for injury to vascular endothelial cells and the initiating factor for atherosclerosis and thrombosis." (PMID 24926346, 2014). "Recent studies showed that D-dimer and hemostatic and inflammatory markers such as von Willebrand factor (vWF; an endothelial marker), CRP and fibrinogen are positively associated with atherosclerosis and CHD." (PMID 24809471, 2014). "In a rabbit model of atherosclerosis, it was shown that endothelial VWF recruited platelets to atherosclerosis-prone sites in response to hypercholesterolemia." (PMID 25152735, 2014).
atherosclerosis (continued). "A mechanism linking VWF to atherosclerosis is based on the fact that VWF mediates platelet adhesion to injured arterial walls, thus delivering platelet contents, including platelet-derived growth factor (PDGF), to the arterial wall." (PMID 22091368, 2010). "Third, while the role of VWF in atherogenesis is debated, arterial thrombosis complicating atherosclerosis appears to be VWF-dependent." (PMID 22091368, 2010). "The potential role of VWF in the development of arterial thrombosis noted in VWD humans with atherosclerosis has been studied in pigs and dogs." (PMID 22091368, 2010). "vWF is a multimeric glycoprotein essential for thrombus formation and the plasma level of it has been shown to be elevated in patients with atherosclerosis." (PMID 20107538, 2009). "Specific arterial geometries resulting from atherosclerosis may enhance pathological thrombus formation after stenosis in a von Willebrand factor-dependent manner." (PMID 40807121, 2025). "Both ACR and vWF could embody endothelial damage and increased permeability, contributing to atherosclerotic plaque formation and atherosclerosis." (PMID 39364405, 2024). "It has also been suggested that vWF is not causally related to atherosclerosis, but rather that the development of atherosclerosis leads to elevated plasma vWF, which favors arterial thrombosis." (PMID 36622519, 2023). "Studies have shown that in the early stages of atherosclerosis, Platelet glycoprotein (GP) Ibα on the platelet membrane can be combined with Von Willebrand Factor (vWF) expressed by injured vascular endothelial cells, which allows platelets to be recruited to atherosclerotic plaques." (PMID 39188346, 2023). "Therefore, this study aimed at demonstrating the presence of C1q-vWF complexes in human atherosclerosis ex vivo." (PMID 38155969, 2023). "Although the elevation of vWF was not as dramatic as HA, which was more than 30 times higher, the accumulation of vWF could somewhat enhance atherosclerosis reducing the athero-protective effects by other ligands in Stab2−/−Apoe−/− mice." (PMID 35360009, 2022). "The high levels of plasma VWF in our study suggest atherosclerosis in branch RVO." (PMID 36137144, 2022). "vWF is a valuable biomarker to determine premature atherosclerosis in RA patients." (PMID 36249997, 2022). "STAB2-binding molecules that are involved in atherosclerosis, including acLDL, apoptotic cells, heparin and vWF were not likely the direct cause of the protection in the Stab2−/−Apoe−/− males." (PMID 35360009, 2022). "Notably, vWF expression can be increased due to atherosclerosis and hypertension and was recently reported to contribute to endotheliopathy from COVID-19 infection." (PMID 34957111, 2021). "This could also be due to the fact that the VWF plays a role not only in endothelial damage at the beginning of the development of atherosclerosis but also in manifest atherosclerosis." (PMID 33448867, 2021). "Considering its possible role in atherosclerosis, as well as in predicting cardiovascular events, increased vWF release could contribute, in particular, to exercise-induced pathological outcomes." (PMID 33593303, 2021). "It is proposed that high shear/vWF-based tests may provide more useful information on adjusting antiplatelet therapy in individual patients with atherosclerosis." (PMID 32529549, 2021). "Some inflammatory markers, such as CRP, ESR, and von Willebrand factor concentration, have been generally considered as having vital roles in the initiation, progression, and complication of atherosclerosis and as independent predictors of mortality and adverse cardiovascular events." (PMID 32375646, 2020). "In addition, VWF is identified as a crucial player in the propagation of atherosclerosis by promoting plaque formation and inflammation." (PMID 32708334, 2020).
atherosclerosis (continued). "Factors promoting thrombosis such as von Willebrand factor (vWF) and P-selectin which are stored in Weibel-Palade bodies (WPBs) of endothelial cells play important roles in the development of thrombosis as well as atherosclerosis (AS)." (PMID 31450612, 2019). "Although various studies suggest that vWF deficiency provides protection from atherosclerosis in animals, in humans, an unequivocal protective effect of vWF deficiency on atherosclerosis has not been demonstrated so far." (PMID 31824501, 2019). "It indicates that GPIbα binding site for vWF, P-selectin, Mac-1 and α-thrombin might be dispensable for atherosclerosis development." (PMID 31572732, 2019). "In this way, the C1q-vWF interaction might be beneficial in dampening inflammation, e.g., in the context of atherosclerosis." (PMID 31824501, 2019). "An important player in the propagation of thrombus formation and atherosclerosis is the blood glycoprotein vWF, which functions as a molecular bridge linking platelets and sub-endothelial collagen after vascular injury and furthermore serves as a chaperone for factor VIII (FVIII)." (PMID 29847840, 2018). "Although this evidence is in animal models, an unequivocal protective role of VWF deficiency in atherosclerosis has not been demonstrated in humans." (PMID 28634421, 2017). "The defects in the secretion of HM VWF upon DDAVP treatment in the ru mice could confer the resistance for atherosclerosis in these mice or HPS6 patients." (PMID 27889498, 2016). "Our study demonstrated significant association of vWF activity and the presence of subclinical atherosclerosis inyoung, non-diabetic, normotensive, female RA patients, with no dyslipidemia." (PMID 26247590, 2015). "According to these results, vWF might be important in very early stages of atherosclerosis, as well as in the later subclinical stage with increased IMT and formation of plaques." (PMID 26247590, 2015). "Correlation of vWF and RF may be a manifestation of a process contributing to the accelerated atherosclerosis in RA." (PMID 26247590, 2015). "We have previously shown that patients with RA of short duration exhibit endothelial activation (expressed by increased level of soluble sVCAM-1, MCP-1, and von Willebrand factor and pentraxin-3) that is an important factor in the development of atherosclerosis." (PMID 25126574, 2014). "The role of VWF in atherosclerosis has been a subject of debate." (PMID 22091368, 2010). "Furthermore, VWF has been reported to have important roles in thrombocyte adhesion and aggregation at the location of increased damaged rates, such as in coronary arteries with atherosclerosis." (PMID 37240845, 2023). "In principle, there are three possible interpretations: First, the reduced C1q-vWF interaction in atherosclerosis could be a non-causal observation." (PMID 38155969, 2023). "In addition, vWF involves in the pathogenesis of atherosclerosis." (PMID 32039706, 2020). "However, our findings unexpectedly point to a beneficial effect of vWF in the context of phagocytosis of CC by macrophages, and suggest that the role of vWF in atherosclerosis might be intricate and requires further investigation." (PMID 31824501, 2019). "Similarly, the role of vWF in atherosclerosis is still a matter of debate." (PMID 31824501, 2019). "Therefore, additional studies are needed to clarify VWF's real role in atherosclerosis." (PMID 28634421, 2017). "Therefore, vWF activity might be a valuable marker of early atherosclerosis in RA patients who may benefit from prevention strategies." (PMID 26247590, 2015). "It has been demonstrated that the impairment of the autophagic machinery in ECs increases the levels of von Willebrand Factor (vWF), P-selectin, VCAM-1, and ICAM-1, which accelerates the development of atherosclerosis." (PMID 39766264, 2024).
atherosclerosis (continued). "The VWF/ADAMTS13 axis connection (bolded) is connected to dementia, mental disorders, autoimmunity, and atherosclerosis, are particularly interesting since changes in this axis appear to regulate vascularization and inflammation." (PMID 33946285, 2021). "We identified several other important proteins whose levels inside circulating EVs were significantly higher in the CSC group than in the HCs and were related to atherosclerosis progression, such as FGC, FN1, and VWF." (PMID 34356850, 2021). "Therefore, vWF might be a valuable marker of early atherosclerosis in RA patients." (PMID 26247590, 2015). "Moreover, atherosclerosis is accelerated and adhesion molecule expression is increased with genetic deletion of ADAMTS13 which cleaves VWF at the A2 domain and removes it from the endothelial surface." (PMID 38693516, 2024). "While the presence of C1q-vWF complexes has been described in the glomeruli of SLE patients with proliferative lupus nephritis, to date, C1q-vWF complexes have not been studied in atherosclerosis." (PMID 38155969, 2023). "Since platelet-endothelial interaction is a contributing factor in atherosclerosis, STAB2 could affect lesion development via vWF/FVIII." (PMID 35360009, 2022). "In the RA group, patients with subclinical atherosclerosis had significantly higher vWF activity compared to those without (134±69 vs. 95±37, p = 0.024) and this association was validated by the logistic regression." (PMID 26247590, 2015). "Subjects with subclinical atherosclerosis or plaque had significantly higher vWF activity than those without (130±68 vs. 97±38, p = 0.026; for plaque 123±57 vs. 99±45, p = 0.028) and this association was verified in the logistic regression analysis." (PMID 26247590, 2015). "The complete absence of VWF in humans (VWD type 3) seems not to protect from atherosclerosis as a study with relatively young individuals (average 37 years) suggested." (PMID 25152735, 2014). "In addition, we will evaluate the effects of probucol and cilostazol combination therapy on the atherosclerosis biomarkers, oxidized LDL, VCAM-1, and vWF." (PMID 21226953, 2011). "Interestingly, a case study of a HMOX1-deficient patient demonstrated that the absence of the enzyme triggered endothelial damage, high plasma levels of von Willebrand factor, increased ICAM-1 expression, coagulation and fibrinolysis defects, generalized inflammation and premature atherosclerosis." (PMID 32611348, 2020). "Therefore, our failure to show enhanced ability of platelets to form firm interactions with fibrinogen and vWF under flow conditions does not undermine the concept of the role of platelets in atherosclerosis development." (PMID 32370146, 2020). "Hence, it is not surprising that results of our research describes signified higher values of vWF as the SPA reaches higher negative values, since higher SPA values have been shown to be associated with atherosclerosis and thrombogenesis." (PMID 29785538, 2018). "Importantly, vWF activity was significantly higher in smokers with subclinical atherosclerosis (6/30) than in those without (24/30) (166±82 vs. 91±31, p = 0.006)." (PMID 26247590, 2015). "However, vWF activity was significantly higher in smokers with subclinical atherosclerosis, than in those without." (PMID 26247590, 2015). "Not much is known about the relevance of human VWF and its receptor complex for atherosclerosis." (PMID 25152735, 2014). "In addition, endothelial specific coagulatory molecules such as von Willebrand factor (VWF), thrombomodulin, plasminogen activator inhibitor-1 antigen, tissue factor, and d-dimer are disturbed in HIV infection, favoring a prothrombotic state, which potentially accelerates atherosclerosis." (PMID 32722629, 2020). "Thus, VWF may mediate thrombotic complications of atherosclerosis rather than atherogenesis per se as discussed next." (PMID 22091368, 2010).